OGA (O-GlcNAcase)
Diseases named in the same sentence as OGA in open-access papers (continued):
Sharing a sentence is not in itself a finding about the gene and the disease.
tumor (continued). "Interestingly, higher OGT and OGA expression levels were observed in tumor samples and cell lines from hematological malignancies compared with those in other solid tumors." (PMID 36104770, 2022). "As a result, OGT and OGA play a pivotal role in tumor progression and prognosis." (PMID 35795059, 2022). "To further verify the relationship between O-GlcNAcylation and the metastasis of CRC, we selected 15 cases of CRC patients with lymph node metastases and detected the expression of O-GlcNAcylation, OGT and OGA in the adjacent tissues, tumor tissues, and lymph node metastases, respectively." (PMID 30093632, 2019). "In contrast, OGA+/− mice were protected from tumor development in Apcmin/+ model of sporadic CRC." (PMID 25915426, 2015). "Translational efforts must prioritise the development of highly specific OGT/OGA inhibitors or allosteric modulators and rigorously validate their efficacy – particularly in rational combination regimens – within preclinical models that recapitulate human tumour heterogeneity and therapy resistance." (PMID 41540817, 2026). "Consequently, OGA emerges as a potential independent predictive marker for tumor recurrence in HCC." (PMID 38116061, 2023). "Immunohistochemistry of OGP, OGT, and OGA in tumor tissues from patients revealed that CCA tissues had increased expression of OGPs which resulted from the increase of OGT and decrease of OGA expression." (PMID 30444036, 2019). "Since O-GlcNAcylation is sensitive to metabolic state and is involved in tumor growth in vitro, we determined the expression of OGT and OGA mRNA." (PMID 30217067, 2018). "Measuring normal pancreas and tumor cell lines showed that OGT protein levels in tumors were higher than in normal cell lines and that OGA levels were decreased." (PMID 24918087, 2014). "Furthermore, APS can trigger ER stress in tumor cells by decreasing the expression of O-GlcNAc transferase (OGT) and increasing the expression of O-GlcNAcase (OGA)." (PMID 38794206, 2024). "Since O-GlcNAcylation is more involved in regulating the expression of oncogenes, precisely targeting OGT/OGA and HBP flux may have greater anti-tumor efficacy." (PMID 38786029, 2024). "Factors in tumor microenvironment can also regulate HBP enzymes and OGT/OGA." (PMID 35201498, 2021). "Besides intracellular signaling proteins, oncogenic signals from tumor microenvironment and virus oncoproteins can regulate O-GlcNAcylation through HBP enzymes and OGT/OGA." (PMID 35201498, 2021). "The inhibition of OGA activity regulated the abundance of proteins relevant to the biology of GBM and, in particular, proteins tightly involved in regulation of inflammation in the tumor microenvironment." (PMID 33902430, 2021). "Tumor progressions were accompanied by increased levels of OGT mRNA and decreasing OGA mRNA." (PMID 24918087, 2014). "Neither OGA nor O-GlcNAc staining correlated with age, sex, recurrence, or tumor size." (PMID 30123425, 2018). "Unfortunately, no data concerning the relationship of OGT and/or OGA (MGEA5) with the presence of an invasive tumor phenotype in malignant head and neck tumors could be found in the literature." (PMID 25315705, 2015). "Thus, our data show that OGA activity is necessary to maintain the normal composition of the GBM secretome, which in turn, may reflect in its protein repertoire the main tumor strategies in response to disturbances imposed on the tumor." (PMID 33902430, 2021).
neurodegenerative disease (13 papers, 2017 to 2026). A disorder of the central nervous system characterized by gradual and progressive loss of neural tissue and neurologic function. "Building on these mechanistic insights, recent advances in small-molecule inhibitors targeting OGA have highlighted their therapeutic potential in neurodegenerative diseases." (PMID 41280891, 2025). "We found that each animal has its unique value for OGT, OGA, OGA activity, mitochondrial activities and parameters of autophagy proteins and proteins involved in neurodegenerative diseases." (PMID 35248135, 2022). "If chronic OGA inhibition is to be developed as a therapeutic tool for neurodegenerative diseases, it is critical that we develop a better understanding of the physiological responses to acute increases in O-GlcNAcylation." (PMID 35248135, 2022). "Our study can provide critical insight about the role of O-GlcNAc in neural maintenance, since inhibitors of OGA are being studied as potential drugs for neurodegenerative disease models." (PMID 33925313, 2021). "In the last decade, OGA inhibitors have been proposed as a promising approach to recover the pathological implications of reduced O-GlcNAcylation in neurodegenerative diseases." (PMID 33258073, 2021). "Inhibition of O-GlcNAcase (OGA), the enzyme responsible for removing protein O-GlcNAcylation, has been explored as a target for modulating brain O-GlcNAc homeostasis in neurodegenerative diseases and may also be a target for OGT-CDG." (PMID 42209020, 2026). "Conversely, OGT or GFAT agonists could be combined with OGA inhibitors to increase O‐GlcNAcylation levels, offering new approaches for neurodegenerative diseases and some autoimmune disorders." (PMID 41394960, 2025). "The extent of this modification has sparked interest in the medical community to explore OGA and OGT as therapeutic targets, particularly in degenerative diseases." (PMID 33669256, 2021).
infection (6 papers, 2014 to 2025). The state of being infected such as from the introduction of a foreign agent such as serum, vaccine, antigenic substance or organism. "O-GlcNAcylation, catalyzed by O-GlcNAc transferase (OGT) and reversed by O-GlcNAcase (OGA), plays a role in regulating processes such as host immune responses and signal transduction during pathogen infection." (PMID 40305291, 2025). "The effects of OGT and OGA inhibitors on A4 O-GlcNAcylation were determined by adding the drugs to cells prior to infection with vA4-YFP and purifying the A4-YFP fusion protein." (PMID 40407344, 2025). "Additionally, in SY5Y cells, we used adenoviral-mediated OGT or OGA infection to alter O-GlcNAc levels." (PMID 25520704, 2014).
metabolic disease (4 papers, 2022 to 2025). A congenital disorder (due to inherited enzyme abnormality) or acquired (due to failure of a metabolically important organ) disorder resulting from an abnormal metabolic process. "Targeting HBP flux or enzymes regulating O-GlcNAc cycling, such as O-GlcNAc transferase (OGT) and O-GlcNAcase (OGA), holds promise for mitigating oxidative stress-related metabolic diseases." (PMID 40700116, 2025). "A constitutive OGA knockout mouse exhibits metabolic disorders, perinatal lethality, organ defects, and tissue-specific dysregulation of O-GlcNAc homeostasis, whereas OGT depletion decreases the proliferation of embryonic neural stem cells and inhibits the migration of newborn neurons." (PMID 35887161, 2022). "However, recent data, obtained with OGT- and OGA-KO mice models, showed that a simplistic scheme in which increased O-GlcNAcylation is considered as deleterious with regard to metabolic diseases does not stand anymore." (PMID 36058931, 2022).
brain disorder (1 paper, 2026). A disease affecting the brain or part of the brain. "O-GlcNAc has been implicated in multiple brain disorders, yet the role of O-GlcNAcase (OGA), the enzyme that removes O-GlcNAc modification from proteins, in dendritic spine regulation remains unclear." (PMID 41534832, 2026).
mitochondrial disease (1 paper, 2023). "Thus, OGA inhibition could aid the brain in combatting the accumulation of dysfunctional mitochondria via stimulating ISRmt in mitochondrial diseases." (PMID 38192280, 2023).
OGA also shares sentences with these, for which no sentence is quoted: Nephropathy (5 papers); renal tubular dysfunction (5); acute kidney injury (3); breast tumor (2); microcephaly (2); acromegaly (1); acute liver failure (1); adenocarcinoma (1); anemia (1); asthma (1); autism (1); bile duct carcinoma (1); breast (1); cardiac hypertrophy (1); cardiovascular disease (1); cecum adenocarcinoma (1); cervical carcinoma (1); chronic kidney disease (1); cognitive decline (1); colon adenocarcinoma (1); colon mucinous adenocarcinoma (1); colonic carcinoma (1); colorectal tumors (1); COVID-19 (1); cryptorchidism (1); diabetic cardiomyopathy (1); diabetic retinopathy (1); endotoxemia (1); erythroblastic leukemia (1); Gaucher disease (1).
A further 27 diseases each share a sentence with OGA in 1 paper.